SEPTIN9 (septin 9)
Diseases named in the same sentence as SEPTIN9 in open-access papers (continued):
Sharing a sentence is not in itself a finding about the gene and the disease.
hereditary neuralgic amyotrophy (8 papers, 2010 to 2025). "Less commonly, there is a hereditary form, hereditary neuralgic amyotrophy, caused by an autosomal dominant mutation in the septin 9 gene of chromosome 17 responsible for cytoskeleton formation." (PMID 39286807, 2024). "Alterations in human septin-9 (SEPT9) levels have been linked to multiple cancers, whereas mutations in SEPT9 cause the episodic neuropathy, hereditary neuralgic amyotrophy (HNA)." (PMID 20502708, 2010). "Mutations in Septin 9 have been found in many, but not all, cases of hereditary neuralgic amyotrophy, making HGS a good candidate gene for other cases of this disease." (PMID 26115514, 2015).
ovarian carcinoma (8 papers, 2008 to 2024). A malignant neoplasm originating from the surface ovarian epithelium. "Septin 9 has also been shown to be in a frequently deleted region in breast and ovarian cancers in loss of heterozygosity (LOH) studies, a finding that further implicates the gene as a possible tumor suppressor." (PMID 19018278, 2008).
melanoma (7 papers, 2014 to 2025). A malignant, usually aggressive tumor composed of atypical, neoplastic melanocytes. "Regarding melanoma pathology, when comparing public data from patients between the diagnosis and metastatic stages, significant frequencies of amplification (14.5% and 10.0% respectively) were observed for the SELENBP1 and SEPTIN9 genes at the metastatic stage." (PMID 39223638, 2024).
rectal cancer (7 papers, 2014 to 2025). A primary or metastatic malignant neoplasm that affects the rectum. "The results show significant hypermethylation of Septin9 in both colon and rectal cancers (P < 0.001)." (PMID 39466813, 2024). "The objective of this study is to evaluate the usefulness of pre-treatment SEPTIN9 gene methylation ratio as a predictor of tumor response to total neoadjuvant therapy and its correlation with tumor size and tumor stage in patients with locally advanced rectal cancer." (PMID 40149300, 2025). "The aim of this study is to evaluate the usefulness of pre-treatment SEPTIN9 gene methylation ratio as a predictor of tumor response to total neoadjuvant therapy and its correlation with tumor size and tumor stage in patients with locally advanced rectal cancer." (PMID 40149300, 2025). "Thus, pre-treatment SEPTIN9 gene methylation ratio correlates with tumor size and N stage and can predict tumor response to total neoadjuvant therapy in patients with locally advanced rectal cancer." (PMID 40149300, 2025). "Septin 9 methylation could be useful as an epigenetic biomarker to confirm a complete clinical response following neoadjuvant therapy in locally advanced rectal cancer, especially when adapted to a non-surgical “watch and wait” protocol." (PMID 35454041, 2022).
colorectal tumors (6 papers, 2011 to 2021). "The presence of methylation of the Septin9 (SEPT9) gene has been shown to be highly correlated to occurrence of colorectal tumor cells." (PMID 22272141, 2011). "This test detects methylated Septin9 DNA in the blood, a known biomarker shed by colorectal tumors." (PMID 33919428, 2021). "The degree of methylation of Septin9 gene is accompanied by the development of colorectal tumors, and appears in the early stage of CRC without obvious tissue changes." (PMID 31088406, 2019).
Cirrhosis (5 papers, 2016 to 2023). A chronic disorder of the liver in which liver tissue becomes scarred and is partially replaced by regenerative nodules and fibrotic tissue resulting in loss of liver function. "We previously reported an elevated expression of septin 9 in HCV-induced cirrhosis: HCV infection increased septin 9 expression and promoted its assembly into filaments, and septin 9 regulated LD growth, dependent on microtubules (MTs)." (PMID 34684276, 2021). "Data revealed a significant upregulation (two-sided Student's t-test, P=0.012) of septin 9 transcriptional expression in cirrhosis samples compared to that in normal liver samples." (PMID 27417143, 2016). "Here, transcriptome analysis reveals a significant upregulation of septin 9 in HCV-induced cirrhosis compared with the normal liver." (PMID 27417143, 2016). "To determine the expression profile of septin 9 in cirrhosis, we used the GSE14323 data set31, including transcriptomes of normal liver (n=19) and HCV-induced cirrhosis samples (n=49)." (PMID 27417143, 2016). "This is a multicenter, nested case-control study, which involves comparing the plasma levels of methylated septin 9 between confirmed HCC cases and patients with cirrhosis (control group)." (PMID 37256650, 2023). "In this study, we investigate the expression of septin 9 and the differential expression of the other septins in HCV-induced cirrhosis." (PMID 27417143, 2016). "With such an approach, epigenetics biomarkers are becoming close to clinical reality, as demonstrated by the example of the circulating, cell-free, DNA-based epigenetic biomarker methylated Septin9, which shows great promise as a tool to diagnose HCC in patients with cirrhosis." (PMID 34572442, 2021). "Despite being involved in carcinogenesis, septin 9 expression and function have not been investigated in precancerous diseases such as cirrhosis." (PMID 27417143, 2016).
leukemia (5 papers, 2009 to 2024). A malignant (clonal) hematologic disorder, involving hematopoietic stem cells and characterized by the presence of primitive or atypical myeloid or lymphoid cells in the bone marrow and the blood. "Septin 9 (SEPT9)a involvement in cancer was first discovered as a fusion product with the MLL gene in leukemia." (PMID 23988185, 2013). "Within this dataset, genes such as CBFB, SEPTIN9, CBFA2T3, CD1A, and ERG have been previously reported to be closely associated with leukemia development and progression. qPCR analysis further confirmed the reduced expression levels of these genes in IRF2BP2‐knockdown cells." (PMID 39454110, 2024).
Pleural effusion (4 papers, 2013 to 2025). The presence of an excessive amount of fluid in the pleural cavity. "The detection of quantitative SHOX2 and SEPTIN9 methylation levels have successfully applied to the diagnosis of colonic adenomas and the detection of malignant cells in pleural effusions and ascites." (PMID 41477641, 2025). "Quantitative SHOX2 and SEPTIN9 promoter methylation levels have been successfully applied for the detection of malignant cells in pleural effusions and ascites." (PMID 36176402, 2022).
colon adenoma (3 papers, 2013 to 2017). An adenoma that arises from the colon. "Despite these differences, both studies provided evidence for a reduced Septin-9 protein level in colon adenoma and in CRC." (PMID 23988185, 2013).
liver fibrosis (3 papers, 2020 to 2024). "The presence of either septin-4 (SEPT4) and septin-9 (SEPT9) was shown to attenuate liver fibrosis by decreasing TGF-beta, alpha-smooth muscle actin, and collagen I production in vivo." (PMID 31936541, 2020).
lung adenocarcinoma (3 papers, 2012 to 2022). A carcinoma that arises from the lung and is characterized by the presence of malignant glandular epithelial cells. "Combined with HOXA9 and SEPTIN9, the detection rates in lung adenocarcinoma (LUAC) were greatly improved from 79.7% to 87.0%." (PMID 36176402, 2022).
Ascites (2 papers, 2016 to 2025). Accumulation of fluid in the peritoneal cavity (between the layers of the peritoneum that lines the abdomen). "The methylation status of SHOX2 and SEPTIN9 genes is significantly correlated with the prognosis of patients with ascites." (PMID 41477641, 2025). "It was suggested that SHOX2, SEPTIN9 and four-gene methylation combined detection were important factors affecting the prognosis of patients with ascites." (PMID 41477641, 2025). "The analysis indicated that methylation of SHOX2 and SEPTIN9 were independent factors affecting the prognosis of patients with ascites." (PMID 41477641, 2025).
neuropathy (2 papers, 2017 to 2025). A disorder affecting the nervous system that manifests with pain, tingling, numbness, and/or muscle weakness. "Here we describe the clinical, electrophysiological, and genetic data of a pediatric HNA patient and provide a literature review of neuropathy phenotypes associated with SEPTIN9 mutation." (PMID 40852410, 2025). "It has been hypothesized that mutations block SEPTIN9 filaments assembly in the cytoskeleton and this pathomechanism is a common base in the molecular etiology of other neuropathies." (PMID 40852410, 2025). "If this shall be confirmed, it is possible that SEPTIN9 gene is involved in a broader spectrum of neuropathies." (PMID 40852410, 2025).
brachial plexus neuritis (1 paper, 2025). An inflammatory process affecting the brachial plexus. "We report a case of 9-year-old girl with brachial plexus neuritis who carries a SEPTIN9 missense mutation inherited from her father." (PMID 40852410, 2025).
cleft lip (1 paper, 2023). Congenital defect in the upper lip where the maxillary prominence fails to merge with the merged medial nasal prominences. "The variant c.1108G > A in gene SEPTIN9 (rs1297513860) was inherited from the mother by heterozygous mode in child 5 with unilateral cleft lip." (PMID 36980938, 2023).
Familial adenomatous polyposis (1 paper, 2023). Familial adenomatous polyposis (FAP) is characterized by the development of hundreds to thousands of adenomas in the rectum and colon during the second decade of life. "Another study (NCT02198092) assesses the suitability of Septin9, a known CRC marker, for CRC detection in individuals with hereditary colon cancer syndromes including LS, Familial adenomatous polyposis (FAP) and MYH-associated polyposis." (PMID 38835740, 2023).
liver disease (1 paper, 2023). "Our study, TENDENCY, aims to validate the novel screening markers (methylated septin 9, urinary volatile organic compounds, and urinary peptides) for HCC diagnosis and study these noninvasive biomarkers in liver disease." (PMID 37256650, 2023).
mucinous carcinomas (1 paper, 2018). "There are six genes (MAL, MYOD1, OSMR, SEPTIN9, SFRP1, and SFRP4) for which hypermethylation is observed almost exclusively or preferentially in mucinous carcinomas." (PMID 29882921, 2018).
nasopharyngitis (1 paper, 2020). An inflammatory process that affects the nasopharynx. "Compared with chronic nasopharyngitis, NPC subjects had a reduced mRNA level of Septin 9 (p < 0.0001), indicating a close association between DNA methylation and transcriptional silencing of Septin 9 in NPC." (PMID 32454907, 2020). "A quantitative methylation-sensitive PCR (qMS-PCR) assay was developed to measure the methylation status and levels of Septin 9 in nasopharyngeal tissues and paired swabs from patients with NPC, chronic nasopharyngitis, and healthy donors." (PMID 32454907, 2020). "In the present study, we determined the methylation status of Septin 9 in nasopharyngeal tissues and corresponding swabs from patients with NPC and chronic nasopharyngitis as well as healthy controls." (PMID 32454907, 2020). "Methylated Septin 9 was detected in 92% (23/25) of NPC tissues and 25% (4/16) of nasopharyngitis controls (p < 0.05)." (PMID 32454907, 2020). "Furthermore, we investigated the mRNA levels of Septin 9 between NPC and chronic nasopharyngitis by qRT-PCR." (PMID 32454907, 2020). "Furthermore, a significantly higher methylation level of Septin 9 was identified in NPC compared with non-NPC controls (NPC vs. nasopharyngitis, p < 0.001; NPC vs. normal, p < 0.001) using Dunn's multiple comparison test." (PMID 32454907, 2020). "Hypermethylated Septin 9 was determined in 16 of 22 (72.7%) NPC, whereas it was found in 2 of 19 (10.5%) nasopharyngitis, but not in any of the healthy controls, showing a significant difference in methylation frequency between NPC and non-NPC (p < 0.01)." (PMID 32454907, 2020). "In addition, methylated Septin 9 was found in 16 (72.7%) nasal swabs from 22 NPC patients, 2 of 19 (10.5%) nasopharyngitis, but not in any of the healthy controls (p < 0.01)." (PMID 32454907, 2020).
cancer (126 papers, 2008 to 2025). A tumor composed of atypical neoplastic, often pleomorphic cells that invade other tissues. "Septin 9 (SEPT9) has been linked to a diverse spectrum of malignancies and appears to be the most notable septin member in that category." (PMID 39334960, 2024). "In cancer-associated stroma, the expression of septin-2 and septin-9 was significantly upregulated, while septin-6 and septin-7 were unchanged." (PMID 32094384, 2020). "Altered expression of Septin 9 (SEPT9), a septin coding for multiple isoform variants, has been observed in several carcinomas, including colorectal, head and neck, ovarian and breast, compared to normal tissues." (PMID 21831286, 2011). "It should be noted that Septin9 has a carcinogenic effect and is an oncogene an oncogene, which might be associated with RA related cancer." (PMID 35006449, 2021). "The Septin 9 gene belongs to a class of GTPases involved in numerous cellular process.The gene has been shown to have multiple alternatively spliced transcripts encoding at least 5 characterized polypeptides designated v1–v5, some of which have been associated with cancer." (PMID 19018278, 2008). "Subsequently, they were verified using qMSP technology in cancer cell lines and clinical plasma samples, leading to the selection of 3 genes — MT-1A, Epo, and Septin9 — for the development of a methylation-based detection method for EC." (PMID 39998886, 2025). "Two extensively studied biomarkers, short stature homeobox 2 (SHOX2) and Septin 9 (SEPT9), have been investigated in various cancer types." (PMID 38339235, 2024). "Cancer Cell Line Encyclopedia (CCLE) transcriptome database analyses confirmed that iCCA cells enriched in septin 9 exhibit epithelial-like features." (PMID 39082897, 2024). "Septin 9 (SEPT9) is associated with a diverse spectrum of neoplasms—abnormal and excessive tissue growth, which covers benign neoplasms and malignant tumors (cancers)." (PMID 39334960, 2024). "In nearly all these cases, except for SEPTIN9, the change induced by DFMO reversed the change associated with cancer." (PMID 36900391, 2023). "The biomarkers short stature homeobox 2 (SHOX2) and Septin 9 (SEPT9) are well characterized in patients with different cancer entities." (PMID 36139516, 2022). "The methylation of SEPT9 (Septin9 gene) inhibits its normal expression, eventually disrupting cell division and leading to cancer." (PMID 36362627, 2022). "The EpiPRO Colon® is first blood test for cancer screening approved by FDA in 2016 that interrogates methylation status of Septin9 (SEPT9) in cfDNA." (PMID 35837109, 2022). "Epi proColon relies on the methylation status of the single gene septin 9 (SEPT9) to infer the presence of cancer and can only achieve a detection sensitivity of 0.48." (PMID 30922396, 2019). "Our and other groups established differential methylation-specific qPCR assays of the stature homeobox 2 (SHOX2) and septin 9 (SEPT9) in various cancer entities with possible biomarker properties for early detection and response prediction strategies." (PMID 27660666, 2016). "The Septin9 marker was developed into the Epi proColon test and evaluated in a case-control setting where the cancer sensitivity was 95% at a specificity of 85%." (PMID 24901436, 2014). "In a prospective trial (PRESEPT NCT00696345) using a CE-marked kit for methylated Septin9 detection, 50.9% of cancers were detected at 91.5% specificity based on a two replicate PCR test." (PMID 24901436, 2014). "These include research on MT-1A, Epo, and Septin9 gene methylation for auxiliary diagnosis at the Cancer Hospital of the Chinese Academy of Medical Sciences (ChiCTR2400083525), which involved a model-verification cohort of 297 participants and a clinical validation cohort of 1429 participates." (PMID 40718833, 2025). "Abnormal hypermethylation of the septin 9 gene was an inchoate incident in some cancers." (PMID 35227194, 2022).
cancer (continued). "As a tumor suppressor gene, the higher methylated level of septin 9 could inhibit gene expression and promote cancer progression." (PMID 34873218, 2021). "Additionally, squamous morphology cancer cell lines aggregated by METHY patterns (C10 [ESCA-HNSC]), particularly in terms of ARHGDIB and SEPTIN9 loss." (PMID 32874774, 2020). "Because it has been shown to be a possible tumor suppressor in human cancers such as ovarian cancer, we hypothesized that Septin 9 may also function importantly in the tumorigenesis of NPC." (PMID 32454907, 2020). "The accumulating evidence for its involvement in human neoplasia indicates that Septin 9 may belong to the class of cancer critical genes." (PMID 32454907, 2020). "The differential effects of septin 9 isoforms on cancer cell migration could be due to protein partners interacting differentially with their specific N-terminal region that might regulate septin assembly or use septins as a docking platform." (PMID 28338090, 2017). "Overexpression of Septin 9 (Sept9) promotes migration of cancer cell lines." (PMID 28338090, 2017). "Septin 9 (SEPT9) in particular was found overexpressed in diverse carcinomas." (PMID 25898316, 2015). "Among some cancer patients, epigenetic changes in the nature of methylation of different gene promoter regions are observed, which affect expression of suppressor genes such as septin 9 (SEPT9)." (PMID 24633736, 2014). "Thus, septin 9 could be seen as the central regulator of the apico–basal polarity of epithelial cells and a guardian against cancer cell migration and invasion, thus remaining an important target in the study of aggressive carcinomas." (PMID 37508480, 2023). "Interestingly, AHNAK has been implicated in the regulation of cell membrane cytoarchitecture, as well as pseudopod protrusion via interaction with Annexin A2, septin-9, and Ca2+-dependent S100 proteins, which have both been shown to contribute to cancer metastasis." (PMID 33564071, 2021). "By using the optimal methylation cutoff value for individual genes, the positive detection rates of each marker in malignant tumor patients ranked from high to low were 46.3% (HOXA9), 45.1% (SHOX2), 31.1% (SEPTIN9) and 18.9% (RASSF1A)." (PMID 41477641, 2025). "Notably, the Ct values in qMSP assays showed that the differentially methylated regions on Septin9, MT-1A, and Epo genes were significantly lower in EC samples compared with controls (Wilcoxon’s test, P < 0.05), indicating these potential markers had a higher methylation status in cancer samples." (PMID 39998886, 2025). "Our findings with the OncoMe panel (SHOX2, RASSF1A, SEPTIN9, and HOXA9) in malignant ascites are consistent with and extend previous reports on DNA methylation biomarkers in body fluids." (PMID 41477641, 2025). "Various studies have reported septin 9 gene (SEPT9) methylation in CRC, highlighting the relevance of SEPT9 methylation in cancer." (PMID 35054365, 2022). "Previous studies confirmed septin 9 gene and protein in CRC tissues played an anti-cancer effect in the generation and development of tumor." (PMID 35227194, 2022). "In conclusion, we found that the aberrant promotor methylation of OncoMe (SHOX2, RASSF1A, SEPTIN9 and HOXA9) was a cancer-specific alteration and might be a valuable marker to aid in the differentiation of MA." (PMID 41477641, 2025). "We compared 5′UTR length between the 85 transcripts with upstream TICs (excluding EPB41L3 and SEPTIN9) with the mRNA sequences of 3615 genes that had no recorded link to cancer." (PMID 36142475, 2022). "Using the network and pathway analysis, Helicase like transcription factor (HLTF) and SEPTIN 9 (SEPT9) genes were selected, since they are more specific than other genes as CRC biomarkers and less involved in the molecular pathways of other diseases and cancers." (PMID 33936232, 2021).